POLR3E (RNA polymerase III subunit E)
Description:
DNA-dependent RNA polymerase catalyzes the transcription of DNA into RNA using the four ribonucleoside triphosphates as substrates. Specific peripheric component of RNA polymerase III (Pol III) which synthesizes small non-coding RNAs including 5S rRNA, snRNAs, tRNAs and miRNAs from at least 500 distinct genomic loci. Assembles with POLR3D/RPC4 forming a subcomplex that binds the Pol III core. Enables recruitment of Pol III at transcription initiation site and drives transcription initiation from both type 2 and type 3 DNA promoters. Required for efficient transcription termination and reinitiation (By similarity). Plays a key role in sensing and limiting infection by intracellular bacteria and DNA viruses. Acts as a nuclear and cytosolic DNA sensor involved in innate immune response. Can sense non-self dsDNA that serves as template for transcription into dsRNA. The non-self RNA polymerase III transcripts, such as Epstein-Barr virus-encoded RNAs (EBERs) induce type I interferon and NF-kappa-B through the RIG-I pathway.
Synonyms: RPC5; SIN; FLJ10509; C37
Tractability: Small molecule: a structure with a bound ligand is known. PROTAC: UniProt records ubiquitination sites on it; ubiquitination databases record sites on it; its protein half-life has been measured.
Gene: Protein-coding gene on chromosome 16 (22,297,375 to 22,335,101, forward strand). Ensembl gene ENSG00000058600.
Subcellular location: Nucleus
Subcellular location (Human Protein Atlas): Nucleoplasm
Pathways (Reactome):
Gene expression (Transcription): RNA Polymerase III Abortive And Retractive Initiation; RNA Polymerase III Chain Elongation; RNA Polymerase III Transcription Initiation From Type 1 Promoter; RNA Polymerase III Transcription Initiation From Type 2 Promoter; RNA Polymerase III Transcription Initiation From Type 3 Promoter; RNA Polymerase III Transcription Termination
Immune System: Cytosolic sensors of pathogen-associated DNA
Gene Ontology:
Biological process: termination of RNA polymerase III transcription; transcription by RNA polymerase III; transcription initiation at RNA polymerase III promoter; DNA-templated transcription
Cellular component: nucleoplasm; nucleus; RNA polymerase III complex; cytosol
Genetic constraint (gnomAD): Loss-of-function variants: 31 observed, 74.72 expected, observed/expected ratio (o/e) 0.41, 90% interval 0.31 to 0.56. The upper end of that interval is the gene's LOEUF score, 0.56, which puts it in group 2 of 6, group 1 being the genes least tolerant of losing a copy. Missense variants: 773 observed, 895.92 expected, observed/expected ratio (o/e) 0.86, 90% interval 0.81 to 0.92. Synonymous variants: 365 observed, 367.04 expected, observed/expected ratio (o/e) 0.99, 90% interval 0.91 to 1.08.
Homologues: Orthologues: chimpanzee POLR3E (99% identical), macaque POLR3E (99% identical), pig POLR3E (95% identical), dog POLR3E (94% identical), rabbit POLR3E (93% identical), mouse Polr3e (93% identical), rat Polr3e (92% identical), guinea pig POLR3E (91% identical), tropical clawed frog polr3e.1 (69% identical), zebrafish polr3e (65% identical), Drosophila melanogaster Polr3E (22% identical), Caenorhabditis elegans W06E11.1 (15% identical).
Diseases named in the same sentence as POLR3E in open-access papers:
POLR3E is named in the same sentence as 9 diseases in open-access papers, as found by Europe PMC text mining. Sharing a sentence is not in itself a finding about the gene and the disease. The quoted sentences say what the papers report.
chickenpox (1 paper, 2022). A contagious childhood disorder caused by the varicella zoster virus. "Heterozygous mutations in genes encoding four Pol III subunits, POLR3A/RPC1, POLR3C/RPC3, POLR3E/RPC5, POLR3F/RPC6, compromise this immune response to Varicella Zoster Virus (chickenpox)." (PMID 35813003, 2022).
cutaneous melanoma (1 paper, 2022). A primary melanoma arising from atypical melanocytes in the skin. "After correcting for multiple testing, the only significant promoters were TERT in cutaneous melanoma and pan-cancer; BCL7A, IGLL5, BCL2, and POLR3E pan-cancer; and HNRNPR in uterine adenocarcinoma." (PMID 36396655, 2022).
encephalitis (1 paper, 2021). An acute inflammatory process affecting the brain parenchyma. "Mutations in the POLR3A, POLR3C, POLR3E and POLR3F subunits are associated with susceptibility to varicella zoster virus-induced encephalitis and pneumonitis." (PMID 34395528, 2021).
POLR3E also shares sentences with these, for which no sentence is quoted: cancer (1 paper); colorectal cancer (1); infection (1); metabolic disease (1); Obesity (1); pneumonitis (1).